PARP1 (poly(ADP-ribose) polymerase 1)
Diseases named in the same sentence as PARP1 in open-access papers (continued):
Sharing a sentence is not in itself a finding about the gene and the disease.
lung disease (3 papers, 2012 to 2023). "Interestingly, oxidative stress–PARP-1–NF-κB axis appears to be tightly linked with inflammatory response in all three-lung diseases despite their distinct pathophysiologies." (PMID 28974953, 2017). "First, our finding that adjunctive PARP inhibition with Tp dampened TB immune responses and potently reduced pathology in mouse lungs suggests that the addition of non-antimicrobial PARP1 inhibitors as adjunctive therapy may benefit the treatment of TB by reducing lung disease." (PMID 38071218, 2023).
meningitis (3 papers, 2014 to 2022). A disorder characterized by acute inflammation of the meninges of the brain and/or spinal cord. "NAD is involved in many metabolic processes, being an essential co-factor for several enzymes, including PARP-1, which plays a crucial role in the development of meningitis-associated central nervous system complications." (PMID 25274277, 2014). "While the activation of PARP1 mediates meningitis-associated CNS complications, the disruption of the PARP1 gene or the inhibition of PARP1 could improve the clinical status of the infected mice." (PMID 36438061, 2022). "Notably, in experimental meningitis, PARP1-deficient mice and mice treated with the PARP inhibitor, 3 aminobenzamide (3-AB), display reduced leukocyte infiltration and meningeal inflammation, and this is correlated with impaired expression of Il1β, Il6 and Nos2." (PMID 25161822, 2014). "PARP1 has an impact on the expression of a range of inflammatory cytokines, such as IL-1β and TNF-α, and promote neuroinflammation, which could result in meningitis, encephalitis, polio, and epidural abscess." (PMID 36438061, 2022).
metastatic melanoma (3 papers, 2013 to 2024). A melanoma that has spread from its primary site to another anatomic site. "In a metastatic melanoma mouse model, targeting PARP-1 through stable expression of shRNA or PARPi improved survival." (PMID 39201718, 2024).
mucosal melanoma (3 papers, 2020 to 2021). A melanoma that arises from a mucosal site. "Little is known about the prognostic significance as well as possible associations between PARP1 and immunologic response in mucosal melanoma." (PMID 32380691, 2020). "Little is known about the possible associations between PARP1 and immunologic response in mucosal melanoma." (PMID 32380691, 2020). "Moreover, in mucosal melanoma, upregulation of PARP1 in neoplastic cells was also associated with an enhanced mitotic index, which confirms a significant role of PARP1 in the regulation of mitosis in melanomagenesis." (PMID 33572647, 2021). "The evaluation of PARP-1 expression as a prognostic factor in mucosal melanomas has also been shown." (PMID 33572586, 2021). "The association between PARP1 and IDO1 and their combined adverse prognostic role raise the potential of combined therapy in mucosal melanoma." (PMID 32380691, 2020). "In the current study of mucosal melanoma, PARP1 overexpression is an independent poor prognostic marker." (PMID 32380691, 2020). "In addition, PARP1 overexpression significantly correlated with high mitotic activity in primary mucosal melanoma, which confirms the important role of PARP1 in regulation of mitosis." (PMID 32380691, 2020). "The association between PARP1 and IDO1 and their combined negative prognostic role raise the potential of combined therapy in mucosal melanoma." (PMID 32380691, 2020). "Increased expression of PARP1 is an independent negative prognostic marker in mucosal melanomas." (PMID 32380691, 2020).
nephritis (3 papers, 2016 to 2022). Inflammation of renal tissue. "Renal ischemia-reperfusion damage is in part mediated by RIPK3 and we have previously shown that absence of PARP1 reduced nephritis severity in male mice, but not females." (PMID 27669412, 2016). "In conclusion, our results demonstrate that RIPK3 is not critical for the development of nephritis not only in males but also in females, suggesting that the necrotic pathway in females is induced by an unknown mechanism, or by a redundant combination of PARP1 and RIPK3-driven pathways." (PMID 27669412, 2016).
non-Hodgkin lymphoma (3 papers, 2010 to 2022). Distinct from Hodgkin lymphoma both morphologically and biologically, non-Hodgkin lymphoma (NHL) is characterized by the absence of Reed-Sternberg cells, can occur at any age, and usually presents as a localized or generalized lymphadenopathy associated with fever and weight loss. "We investigated whether PARP-1 polymorphisms are associated with the risk of non-Hodgkin lymphoma (NHL)." (PMID 20196871, 2010).
pancreatitis (3 papers, 2014 to 2024). Inflammation of the pancreas. "Conceivably, the protective effects of PARP-1 antagonism in organs other than the pancreas could be secondary to alleviation of pancreatitis." (PMID 27465581, 2016). "After the administration of PJ34, 3-AB, or other inhibitors, pancreatitis and lung-related damage in SAP mice were markedly alleviated, suggesting that decreasing or decreasing PARP1 expression can minimize LPS-induced AP damage and lung damage." (PMID 39421730, 2024).
retinoblastoma (3 papers, 2013 to 2020). A malignant tumor that originates in the nuclear layer of the retina. "Therefore, we propose including PARP1 inhibitors in the existing DSB inducing chemotherapies developed for treating retinoblastoma and other RB-deficient cancers." (PMID 33271982, 2020). "The EGP2-TK-2T transfected retinoblastoma cell lines treated with GCV drug showed the apoptotic marker, activated Caspase3 and necrotic marker PARP-1 expression (lanes 3, 4) but not in normal cell lines (lanes 1, 2)." (PMID 24391761, 2013).
Salmonella Infections (3 papers, 2009 to 2022). Infections with bacteria of the genus SALMONELLA. "PJ-34, a potent poly (ADP-ribose) polymerase-1 (PARP-1) inhibitor, may exert defense on intestinal epithelial cells (IECs) against invasive Salmonella infection by up-regulating IL-6 production through the ERK and NF-κB signal pathway." (PMID 34943999, 2021).
sarcopenia (3 papers, 2014 to 2024). Progressive decline in muscle mass due to aging which results in decreased functional capacity of muscles. "PARP-1 acetylation also leads to the stimulation of NF-κB dependent gene expression, which leads to increase in inflammation, one of the hallmarks of sarcopenia." (PMID 36818553, 2023). "Together these results suggest that the inhibition of PARP-1 may be an effective way to rescue skeletal muscles from ROS/PARP-1-induced decline in muscle performance (e.g., delay the onset of fatigue and increase the total sustained work) in sarcopenia." (PMID 25361036, 2014). "Furthermore, data from our present study suggest that skeletal muscles from young and aged mice differentially regulate protein PARylation and that PARP-1 might be one of the downstream targets of the stress stimuli that initiate sarcopenia." (PMID 25361036, 2014).
status epilepticus (3 papers, 2015 to 2019). Status epilepticus is defined as a continuous seizure lasting more than 30 min, or two or more seizures without full recovery of consciousness between any of them. "Recently, we revealed that PARP1 regulates the differential neuronal/astroglial responses to pilocarpine-induced status epilepticus (SE) in the distinct brain regions." (PMID 26388738, 2015).
T-cell lymphomas (3 papers, 2015 to 2020). "Mice lacking PARP1 exhibit high levels of sister chromatid exchange, increased chromosomal aberrations, including fusions, breaks, and telomere shortening, and double-mutant DNA-PK/PARP1-deficient mice develop a high frequency of T-cell lymphomas." (PMID 32075244, 2020). "Moreover, double-deficiency in PARP-1/PARP-2 in T-cells led to highly aggressive T-cell lymphomas with long latency." (PMID 28181505, 2017). "Again, the potential clinical relevance of these observations is shown by the similarly increased phosphorylation of histone 2AX and cleavage of PARP1, caspase 3 and caspase 9 in the T-cell lymphoma patient cell sample exposed to romidepsin." (PMID 26473529, 2015).
xeroderma pigmentosum group A (3 papers, 2016 to 2021). Any xeroderma pigmentosum in which the cause of the disease is a mutation in the XPA gene. "Increased DNA damage response through hyperactivation of PARP-1 [poly (ADP-ribose) polymerase-1] can inhibit mitophagy by disrupting the NAD+-sirtuin-PGC-1α axis in cells developed from xeroderma pigmentosum group A patients." (PMID 28424571, 2017). "PARP-1 activation also occurs in neurodegenerative DNA repair disorders including xeroderma pigmentosum group A (XPA) and Cockayne syndrome group B (CSB), and treatment with specific PARP inhibitors rescues defective phenotypes in XPA mutant worms and CSB mutant mice respectively." (PMID 27465020, 2016).
acute leukemia (2 papers, 2018 to 2022). A clonal (malignant) hematopoietic disorder with an acute onset, affecting the bone marrow and the peripheral blood. "Recently, the potential synergistic effects of combining WEE1 and PARP1 inhibition in acute leukemia revealed also a potential synergistic effect, creating a double-hit model by increasing DNA damage and preventing DNA damage repair." (PMID 29489886, 2018).
age (2 papers, 2009 to 2026). A temporal measurement of the time period elapsed since an identifiable point in the life cycle of an organism. "As central integrator, PARP1 maymediate cellular stress response pathways and thereby participate in amultitude of age-related pathologies." (PMID 20157531, 2009).
astrocytomas (2 papers, 2017 to 2024). "Our findings underline that PARP1 is a marker candidate of higher-grade in astrocytomas, presumably because higher PARP1 expression facilitates the repair of damaged DNA and, thereby, overcomes the genetic instability characteristics of tumour cells." (PMID 28654422, 2017). "To the best of our knowledge, we hereby present the first comprehensive study that evaluate I) PARP1 CNAs and mRNA expressions, II) its usefulness in GBM subtype prognosis, and III) the associations of PARP1 with specific astrocytoma molecular markers." (PMID 28654422, 2017). "We demonstrated that PARP1 gain and increased mRNA expression are characteristics of high-grade astrocytomas, particularly of Proneural and Classical GBM subtypes." (PMID 28654422, 2017). "We found, that grade II tumours have the lowest CNA rate (0.036) followed by grade III astrocytomas (0.167) and grade IV GBM (0.215), and high PARP1 copy numbers correlate with higher histological grades (p<0.001)." (PMID 28654422, 2017). "Increased PARP1 mRNA levels were found in the high-grade tumours as opposed to grade II astrocytomas (GII vs. GIII, p=0.003, and GII vs. GIV, p<0.001)." (PMID 28654422, 2017). "Although PARP1 inhibition is a promising therapeutic target, no comprehensive study has addressed PARP1's expression characteristics and prognostic role regarding molecular heterogeneity in astrocytomas including GBM." (PMID 28654422, 2017).
Autoimmunity (2 papers, 2013 to 2016). The occurrence of an immune reaction against the organism's own cells or tissues. "Inhibition of PARP-1 activity by its inhibitors or by gene mutation in mice has been shown to lead to suppression of chronic inflammation and autoimmunity." (PMID 23977081, 2013). "Necrotic cell death plays a significant role in the pathogenesis of autoimmunity and necrotic pathways mediated by PARP1 and RIPK3 are among the best characterized." (PMID 27669412, 2016).
B cell lymphopenia (2 papers, 2020 to 2021). "Similarly, B cell lymphopenia in dual PARP-1/PARP-2-deficient mice can affect the recruitment of B cells to the tumor microenvironment." (PMID 32046278, 2020).
benign prostatic hyperplasia (2 papers, 2018 to 2023). A non-cancerous nodular enlargement of the prostate gland. "Additionally, these observations align with studies demonstrating that PARP‐1 and PAR are elevated in PCa compared to benign prostatic hyperplasia in a Chinese cohort and that PARP‐1 protein is elevated in cases of primary PCa as compared to normal controls." (PMID 30467127, 2018).
breast-invasive carcinoma (2 papers, 2017 to 2021). "After bioinformatics analysis, we found that the expression levels of FOXM1 and PARP1 were higher in breast invasive carcinoma tissue than in adjacent tissue." (PMID 34880209, 2021). "In the present study, we examined the subcellular expression of NHERF1, BRCA1 and PARP1 proteins in invasive breast carcinomas and investigated, for the first time, the relationship among their expression and with patient outcome." (PMID 29029467, 2017). "FOXM1 expression was positively correlated with PARP1 expression in breast-invasive carcinoma." (PMID 34880209, 2021).
calcification (2 papers, 2020 to 2023). Process by which organic tissue becomes hardened by the physiologic deposit of calcium salts. "Recently, activation of oxidative stress and/or DNA damage response (DDR) pathways, in particular poly(ADP-ribose) polymerase 1 (PARP1) signaling at sites of ectopic calcification, was found to play an important role in vascular calcification." (PMID 37894722, 2023).
cervical tumor (2 papers, 2017 to 2019). "Our data demonstrates significantly higher expression of PARP1 in primary cervical tumors and CC cell lines SiHa and ME180." (PMID 28993682, 2017). "Proteins such as STAT3, TGFβ3, LEFTY A, PARP1, and ZFX are also expressed in cervical tumor samples." (PMID 31885625, 2019).
chronic pancreatitis (2 papers, 2021 to 2022). A chronic inflammatory process causing damage and fibrosis of the pancreatic parenchyma. "Activation of PARP1 contributes to tissue injury and inflammation in acute and chronic pancreatitis." (PMID 35740393, 2022). "In conclusion, we identified an active role of PARP1 in chronic pancreatitis." (PMID 33808340, 2021). "However, the role of PARP1 and PARylation has not yet been investigated in chronic pancreatitis." (PMID 33808340, 2021).
cocaine addiction (2 papers, 2017 to 2021). "Recently, PARP-1 and PARylation have been described as a novel regulator of cocaine addiction and reward." (PMID 28828398, 2017). "Therefore, miR-125b alone or by upregulating PARP-1 expression may regulate dendritic spine structure that plays important role in the behavioral response to cocaine addiction." (PMID 28828398, 2017). "Recently, the role of poly(ADP-ribose) polymerase-1 (PARP-1) was identified in plasticity, memory, and cocaine addiction." (PMID 34756133, 2021).
colon adenoma (2 papers, 2014 to 2021). An adenoma that arises from the colon. "Immunohistochemical studies have shown that in colon adenomas and carcinomas the amount of proteins identified by anti-PARP-1 antibody was significantly higher than in surrounding colon tissue without histological changes." (PMID 25526641, 2014). "PARP-1 expression is also increased in colon adenoma and carcinoma." (PMID 33572586, 2021). "Indeed, several studies have demonstrated that the expression of OGG1 and PARP-1 is enhanced as a result of oxidative stress, and our recently published paper has shown increased oxidative stress in colon adenoma and carcinoma patients." (PMID 25526641, 2014).
colorectal adenoma (2 papers, 2018 to 2025). An adenoma that arises from the colon or rectum. "So, the hypothesis of association of this variant with colorectal adenoma is because of the linkage disequilibrium with another variant in PARP1 promoter is supported by our findings in current study." (PMID 30183716, 2018). "This study identified NUDT13 as a roadblock in the progression from colorectal adenoma to CRC, and revealed that NUDT13 stabilizes PKM1 protein by reducing the PARylation that is catalyzed by PARP1, thereby reprogramming the metabolic propensity of CRC cells." (PMID 39921866, 2025). "In conclusion, we identified NUDT13 as a roadblock in the progression from colorectal adenoma to CRC, and revealed that NUDT13 stabilizes PKM1 protein by reducing the PARylation that is catalyzed by PARP1, thereby reprogramming the metabolic propensity of CRC cells." (PMID 39921866, 2025).
demyelinating disorders (2 papers, 2022 to 2023). "The shared underlying mechanisms driving malignancy and demyelinating disease, together with the success of anticancer drugs as repurposed therapeutics, makes the repurposing of PARP-1 inhibitors for demyelinating diseases a worthy concept to consider." (PMID 35158955, 2022). "Our data support the idea that sulfatide is a key driver of demyelination and neuroinflammation in MLD and suggest that PARP-1 inhibitors have therapeutic utility in the sphere of rare demyelinating disease." (PMID 37525026, 2023). "Here, we present the current knowledge on the role of PARP-1 in the CNS, its implication in diseases of the CNS, and its potential as a therapeutic target in neurological inflammatory and demyelinating diseases." (PMID 35158955, 2022). "Here, we present existing evidence that implicates PARP-1 as a player in the development and progression of both malignancy and demyelinating disease." (PMID 35158955, 2022). "In this review, we discuss the potential for repurposing PARP-1 inhibitors, with a focus on rare demyelinating diseases." (PMID 35158955, 2022). "Further insights into the function of PARP-1 in brain homeostasis and dysregulation in pathological states may assist in the development of PARP-1 inhibitors for rare demyelinating diseases such as leukodystrophies." (PMID 35158955, 2022).
dyslipidemia (2 papers, 2009 to 2018). "We also examined the relationship between occurrence of oxidative stress in our experimental model and PARP-1 activation as a potential mechanism for the manifestation of dyslipidemia-associated vascular and autonomic nervous system dysfunction." (PMID 19823587, 2009). "In this study, we demonstrate that PARP-1 plays an important role in both dyslipidemia-associated vascular and autonomic dysfunction." (PMID 19823587, 2009). "The study revealed that PARP-1 plays an important role in dyslipidemia-associated vascular and autonomic dysfunction." (PMID 19823587, 2009). "The aims of this study were to investigate the role of poly(ADP-ribose) polymerase (PARP)-1 in dyslipidemia-associated vascular dysfunction as well as autonomic nervous system dysregulation." (PMID 19823587, 2009). "In conclusion, using conscious animals we have demonstrated that PARP-1 participates in dyslipidemia-mediated vascular dysfunction and dysregulation of autonomic function and that PARP-1 gene deletion is protective against these defects." (PMID 19823587, 2009). "Dyslipidemia induced PARP-1 activation was accompanied by oxidative tissue damage, as evidenced by increased expression of iNOS and subsequent protein nitration." (PMID 19823587, 2009). "The results of the present investigation demonstrate that PARP-1 participates in dyslipidemia-mediated vascular dysfunction and dysregulation of autonomic function and that PARP-1 gene deletion is protective against these defects." (PMID 19823587, 2009). "Atherogenic index, which has been suggested as better index of dyslipidemia and important tool to analyze the results considering the complexity of lipoproteins was significantly decreased by PARP-1 gene deletion in both RD and HF regimen." (PMID 19823587, 2009). "This study demonstrates that PARP-1 participates in dyslipidemia-mediated dysregulation of the autonomic nervous system and that PARP-1 gene deletion normalizes autonomic and vascular dysfunctions." (PMID 19823587, 2009).